BRCA2 (BRCA2 DNA repair associated)
Diseases named in the same sentence as BRCA2 in open-access papers (continued):
Sharing a sentence is not in itself a finding about the gene and the disease.
prostate carcinoma (continued). "While the loss of BRCA2 function and its consequences in prostate cancer is being reconsidered, BRCA2 is generally regarded as a “tumor suppressor”, with an established role in maintaining genomic stability via its function in the homologous recombination pathway for double-strand DNA repair." (PMID 20805891, 2010). "The lack of prostate carcinoma in our mutants may reflect the relatively low penetrance of prostate cancer in human BRCA2 mutation carriers and suggests there is only a subset of BRCA2 carriers that develop aggressive forms of the disease." (PMID 20585617, 2010). "In prostate cancer BRCA2 has been associated to promotion of invasion through upregulation of MMP9." (PMID 20805891, 2010). "One gene that has consistently been associated with prostate cancer is BRCA2 (see Review article)." (PMID 19476645, 2009). "Germline mutations in the BRCA2 gene have been suggested to account for about 5% of familial prostate cancer; mutations have been reported in 2% of early onset (i.e., ≤ 55 years) prostate cancer cases and a segregating founder mutation has been identified in Iceland (999del5)." (PMID 19476645, 2009). "Germ line mutations of BRCA2 were also linked to early-onset prostate cancer." (PMID 19826425, 2009). "An excess risk of prostate cancer among men with BRCA2 mutations has been previously documented." (PMID 18577985, 2008). "Ideally, one would follow a cohort of unselected patients with prostate cancer and a BRCA2 mutation, record details on the stage, grade and all treatments received, and then compare the outcome of the hereditary group with a similar group of patients without a mutation." (PMID 18577985, 2008). "Given that the BRCA2 protein is involved in the repair of damaged DNA breaks, and that radiation induces double-strand breaks, it is possible that prostate cancer patients with a BRCA2 mutation are more sensitive to radiotherapy than patients without a mutation." (PMID 18577985, 2008). "The presence of a BRCA2 mutation was associated with a 4.8-fold increased risk of prostate cancer." (PMID 18577985, 2008). "Men with BRCA2 mutations have been found to be at increased risk of developing prostate cancer." (PMID 18577985, 2008). "A recent study from Iceland suggests that prostate cancers in men with a BRCA2 mutation may be unusually aggressive." (PMID 18577985, 2008). "However, the population attributable risk of prostate cancer in US Caucasians under age 55 due to carrying one of these rare germline protein-truncating BRCA2 mutation is estimated to be <1%." (PMID 17700570, 2007). "A more complete understanding of the role of the BRCA2 gene in relationship with prostate cancer susceptibility may provide insight on prostate carcinogenesis." (PMID 17700570, 2007). "However, we estimate that <1% of early-onset prostate cancers in the general US Caucasian population can be attributed to these rare disease-associated BRCA2 mutations." (PMID 17700570, 2007). "Prostate cancer risk is also higher in BRCA2 compared to BRCA1 carriers." (PMID 17213823, 2007). "The contribution of germline BRCA1 and BRCA2 mutations to prostate cancer incidence is probably small and could be limited to specific subgroups." (PMID 9743298, 1998). "Finally, at the gene-level, we tested for genetic association between aggressive prostate cancer and controls, and found that PTVs in BRCA2 (OR = 8.23 [6.17–10.85], P = 1.47 × 10−36) and ATM (OR = 5.27 [3.65–7.46], P = 1.74 × 10−16) were significantly associated with aggressive disease." (PMID 39971927, 2025). "Fifteen variants in BRCA1 and 28 variants in BRCA2 were filtered out due to insufficient evidence in ClinVar, with a high fraction (47% and 71%, respectively) identified on-tumor (i.e., in breast/ovarian/pancreatic/prostate cancers), as expected for true pathogenic germline variants." (PMID 37568048, 2023).
prostate carcinoma (continued). "In addition, among localized prostate cancers under active surveillance in the United States, prostate cancer patients with germline BRCA1/BRCA2 or ATM pathogenic variants were 1.96 times more likely to be upgraded on re-biopsy specimens than prostate cancer patients without pathogenic variants." (PMID 37174127, 2023). "This case demonstrated that the carboplatin could have a dramatic antitumor effect on patients with prostate cancer with germline BRCA2 mutations and family history will help to ensure that patients and their families can be provided with proper genetic counseling." (PMID 34425813, 2021). "However, the clinical relevance of germline and somatic defects in DDR genes remains largely unclear at present—the exception being germline BRCA2 mutations, which have been shown to be an independent prognostic factor for prostate cancer outcomes in different settings." (PMID 33106584, 2021). "In addition, a study of 13 adult family members of deceased men with early-onset prostate cancer who had participated in a study and who had been found to have a BRCA2 mutation showed that some participants experienced distress and anxiety, although this was resolved through genetic counseling." (PMID 34748551, 2021). "Interestingly we observed that prostate cancer, particularly diagnosed over age 60, was a significant predictor of BRCA2 pathogenic variant status in men, with relatively strong effects of both personal and family history of prostate cancer in Hispanics and African Americans." (PMID 31853058, 2020). "This could be of interest in setting testing criteria in these populations and may be due to a higher prevalence of aggressive prostate cancer in these populations and/or to higher Gleason scores in these populations that are known to be associated with germline BRCA2 pathogenic variants." (PMID 31853058, 2020). "However, several retrospective reports have suggested that BRCA2 mutated prostate cancer may be highly sensitive to this therapy." (PMID 30871108, 2019). "The authors noted that the contribution of difficult-to-detect variant types, paired with the fact that tumor sequencing studies often do not systematically assess germline alleles, might underlie the low reported frequency of BRCA2 mutations in earlier prostate cancer sequencing studies." (PMID 28525389, 2017). "Hence, the aim of the present study is to determine whether loss of heterozygosity (LOH) in RAD51, BRCA1, and BRCA2 contributes to the sporadic prostate cancer." (PMID 26433958, 2015). "This suggests BRCA2 may be a high risk prostate cancer susceptibility gene." (PMID 26236408, 2015). "In addition, BRCA2 mutation carriers have been associated with aggressive prostate cancer." (PMID 20585617, 2010). "In each linked pedigree, we selected the youngest prostate cancer case that carried a segregating haplotype of interest as well as the most distantly related individual in the pedigree who also carried the same segregating haplotype for BRCA2 mutation screening." (PMID 19476645, 2009). "Heterozygous pathogenic GVs in BRCA2 are associated with HRR deficiency and susceptibility to female breast, male breast, esophageal, gastric, pancreatic, ovarian, and prostate cancer." (PMID 41546701, 2026). "The first case is a 72-year-old male with a history of prostate cancer and GIST, where genetic testing revealed germline variants in BRCA2 and SDHA." (PMID 41635891, 2026). "For instance, male pathogenic BRCA2 variant carriers are advised to undergo prostate-specific antigen (PSA) testing starting at age 40, given their significantly increased risk for prostate cancer." (PMID 41528496, 2026). "The case highlights the vigilance for atypical paraneoplastic manifestations, the need for early genomic testing, and the exploration of novel therapeutic strategies in BRCA2-driven prostate cancer." (PMID 41669591, 2026).
prostate carcinoma (continued). "Individuals with pathogenic BRCA variants face an elevated risk not only for breast and gynecologic cancers but also for pancreatic cancer (BRCA1: 1–3%, BRCA2: 3–5% by age 70), and male carriers for prostate cancer (BRCA1: 21%, BRCA2: 27% by age 75)." (PMID 41528496, 2026). "Some studies suggested that BRCA1 pathogenic variants tend to be associated with aggressive prostate cancer (OR = 1.2–2.0); however, the lower carrier frequency of BRCA1 (0.2%) compared with BRCA2 (1.1%) limits the statistical power." (PMID 41423785, 2026). "BRCA1 exon 22 and BRCA2 exon 27 have been reported in advance prostate cancer pathogenesis due to homologous recombinant repair defects." (PMID 40725150, 2025). "BRCA1 and BRCA2 have emerged as critical biomarkers in advanced prostate cancer, given their essential roles in homologous recombination repair and genomic stability." (PMID 40725150, 2025). "The cumulative risks to those at age 80 are reported as being approximately 2.5% for pancreatic cancer for both BRCA1 and BRCA2 carriers, and 27% for prostate cancer for BRCA2 carriers." (PMID 39996890, 2025). "In this continuous clinical evaluation, BRCA2 is the most frequently identified prostate cancer gene with over 10% involvement in metastatic disease." (PMID 40046829, 2025). "We detected prostate cancer ISUP 2 or higher diagnosis in 8% and 47% of men with LP/P BRCA1 and BRCA2 variants, respectively, compared to the IMPACT study showing ISUP 2 or higher diagnosis in 45% and 63% of men with BRCA1 and BRCA2 variants, respectively." (PMID 39838196, 2025). "The current study has shown a high frequency of BRCA2 involvement in both metastatic and familial prostate cancer of ~10%, including somatic PVs." (PMID 40046829, 2025). "Mutations in specific genes, such as BRCA1, BRCA2, and HOXB13, have been identified as contributors to hereditary prostate cancer." (PMID 40852019, 2025). "Here, we validate BRCA2, ATM and CHEK2 deleterious rare variants as significant risk factors, and reproduce the recently described association of SAMHD127 with prostate cancer in UKB and replicate the finding in additional cohorts." (PMID 39971927, 2025). "For example, in prostate cancer, pathogenic germline variants in DNA repair genes (ATM, CHEK2, PALB2, BRCA2) vary by ancestry; some are enriched or even unique to specific populations, leading to differences in prevalence and risk across groups." (PMID 41573212, 2025). "Our research shows that the RFLP-based detection of BRCA2 and HOXB13 mutations can enhance the diagnostic process of prostate cancer, particularly for early detection." (PMID 40433050, 2025). "As the first FDA-approved anti-cancer drug that exploits the concept of synthetic lethality, PARP inhibitors (PARPi) are widely employed to treat breast, ovarian, pancreatic, and prostate cancer patients associated with BRCA1 and BRCA2 mutations." (PMID 40299557, 2025). "Of familial prostate samples with no family history of breast, ovary or pancreatic cancer, 0/33 with a Manchester score for BRCA2 of ≥4 equivalent to two prostate cancers<60 or one<60 and two over 60 had a gBRCA." (PMID 40046829, 2025). "A study by The Prostate Cancer Transatlantic Consortium (CaPTC) utilizing whole exome sequencing to determine genetic variants in Nigerian patients with advanced prostate cancer identified high frequencies of mutations in the BRCA1, BRCA2, APC, and ATM genes." (PMID 40313245, 2025). "BRCA2 and HOXB13 mutations significantly increase the risk of prostate cancer, demonstrating the predictive power of genetic testing for early diagnosis and risk management." (PMID 40433050, 2025). "In BRCA1/2-mutant HGSOC and BRCA2/ATM-mutant prostate cancer, M2 macrophages exhibit a preferential accumulation within regions of proliferating tumor cells." (PMID 40830526, 2025).
prostate carcinoma (continued). "For female breast and prostate cancer, a significant interaction between BRCA2 and PGS was found (HR < 0.83, p < 0.05); the effect of PGS on cancer risk was weaker in carriers than noncarriers." (PMID 40462315, 2025). "Genes linked to prostate cancer susceptibility, including RNASEL, MSR1 and MIC1, found in areas associated with familial prostate cancer, as well as TLR4, MIC1, PON1, BRCA2, CHEK2 and OGG, have been identified as contributors to prostate cancer development." (PMID 38971935, 2025). "We also observed the genes associated with DNA repair and aggressive prostate cancer risk (BRCA1 and BRCA2)." (PMID 41463218, 2025). "We also found increased CBC and prostate cancer risks in male BRCA2 PV carriers and elevated colorectal and pancreatic cancer risks in female BRCA1 and BRCA2 PV carriers." (PMID 39475295, 2025). "In summary, our investigation supports a role for BRCA2 and HOXB13 mutations in prostate cancer predisposition and provides reassurance that BRCA1, RNASEL, and ELAC2 are not substantially contributory in this cohort." (PMID 40433050, 2025). "The genotyping data showed 39 subjects with mutations of prostate cancer cases from PCR- RFLP analysis, including 26 positives for BRCA2 and 13 positives for HOXB13 mutations." (PMID 40433050, 2025). "We have also shown a threefold higher prevalence of prostate cancer among BRCA2 heterozygotes with the expected higher death rates." (PMID 40046829, 2025). "Collectively, these results provide strong evidence that mutations in BRCA2 and HOXB13 are associated with an increased risk of prostate cancer and highlight their role as potential genetic markers for early detection and risk stratification." (PMID 40433050, 2025). "Germline mutations, such as those in BRCA1, BRCA2, and HOXB13 genes, can confer an increased risk of prostate cancer." (PMID 40432836, 2025). "Here, we present a patient with a rare coexistence of both BRCA2 and PSM2 mutation in the setting of metastatic pancreatic and prostate cancer." (PMID 40880847, 2025). "An improved understanding of individual risk would account for ethnicity, advancing age, family history of prostate cancer, and genetics (eg, mutations in BRCA1, BRCA2, ATM, and the mismatch repair genes)." (PMID 38583453, 2024). "A pivotal role in prostate cancer biology is played by the tumor suppressors BRCA1 and BRCA2, belonging to the homologous recombination deficiency (HRD) repair system, that enables the error-free recovery of double strand breaks (DSBs)." (PMID 39335746, 2024). "To further determine the correlation between BRCA2 mutations and AURKB expression in prostate cancer patients, we collected samples from prostate cancer patients with intact and mutant BRCA2, and analyzed the AURKB level using immunohistochemistry." (PMID 37934606, 2024). "Today, PARP-inhibitors are currently used for the treatment of prostate cancer patients with germinal or somatic mutations in BRCA1 and BRCA2 genes, which results in therapeutically resistant cancers." (PMID 39335746, 2024). "The use of PARPis in prostate cancer relies on the detection of mutations in several homologous recombination genes in addition to BRCA1 and BRCA2." (PMID 38612902, 2024). "Survival screenings of C. elegans identifies pathways and genes responsible for BRCA2-induced lethality in prostate cancer models." (PMID 37934606, 2024). "Our data confirmed that shRNA mediated stable knockdown of well-known HR genes BRCA2/ATM in a prostate cancer cell line model led to 8- to 12-fold increased sensitivity toward LP-184, as compared with only 2- to 8-fold increased sensitivity toward olaparib." (PMID 38630886, 2024).
prostate carcinoma (continued). "It has been reported that increased SKP2 expression following the adhesion of prostate cancer cells to basement membranes leads to the degradation of BRCA2 and promotes cell proliferation." (PMID 39062881, 2024). "In conclusion, these data indicate that PARP inhibitors exert a powerful selective pressure for BRCA reversion mutations in BRCA-mutant tumors, as evidenced by extensive convergent evolution in a patient with BRCA2-mutant prostate cancer." (PMID 38355834, 2024). "Regarding prostate cancer, we found only 1 case report with BRCA2 inactivation; skin disease response to docetaxel and subsequent liver involvement as a final progression of the disease were also described." (PMID 39465866, 2024). "Once individuals reach the age of 40, it is recommended to start prostate cancer screening for BRCA2 carriers." (PMID 38339330, 2024). "On the basis of the most relevant literature results, we describe an overview of our NGS BRCA1 and BRCA2 data of prostate cancer patients’ FFPE samples, and we highlight technical procedures performed and relevant clinical implications." (PMID 39335746, 2024). "This case report describes a 75-year-old man with BRCA2-positive metastatic castrate-resistant prostate cancer who developed aplastic anemia after taking olaparib." (PMID 39175508, 2024). "Deleterious germline variants of BReast CAncer susceptibility genes BRCA1 and BRCA2 (BRCA) significantly increase the risk of developing “BRCA mutation”-related tumors, including breast, ovarian, pancreatic, and prostate cancer." (PMID 38566028, 2024). "BRCA1 and BRCA2 sequencing data obtained from tissue somatic DNA of prostate cancer patients were analyzed." (PMID 39335746, 2024). "According to the literature, the prevalence of BRCA2 alterations in primary prostate cancer is significantly lower than that in mCRPC." (PMID 39172235, 2024). "In contrast, male relatives of BRCA2 carriers had significantly higher risks of pancreatic (RR = 4.34, 95% CI = 2.17-8.68; P = 0.001) and prostate cancers (RR = 4.86, 95% CI = 2.20-10.75; P = 0.001) than male relatives of non-carriers." (PMID 36861435, 2023). "By associating MuAt features with driver events identified in PCAWG, MuAt highlighted prostate cancers driven by SPOP mutations, characterized by a 2.3-fold increase in somatic SV burden, exceeding the relative burden in tumours with BRCA1 and BRCA2 mutations." (PMID 37420249, 2023). "Mutations in breast cancer gene 1 (BRCA1) and breast cancer gene 2 (BRCA2) have been associated with male breast cancer (MBC), as well as prostate cancer (PCa)." (PMID 38161833, 2023). "Pathogenic variants in genes such as BRCA1 and BRCA2 mismatch repair genes and HOXB13 confer modest to moderate lifetime risk of prostate cancer." (PMID 37345060, 2023). "The most-studied biomarkers were BRCA 1 and BRCA2, with 17 articles providing the data of their expression level in clinical prostate cancer samples." (PMID 37444562, 2023). "HRD phenotypes in breast, ovarian, pancreatic, and prostate cancers have been associated with germline and somatic mutations as well as suppression of epigenetic modifications in BRCA1 and BRCA2." (PMID 37808268, 2023). "Homology recombination repair (HRR) is the DNA damage repair (DDR) mechanism most frequently altered in prostate cancer; of note BRCA2 is the most frequently altered DDR gene in this tumor." (PMID 36793600, 2023). "In the current study, the set of genes (ATM, BRCA2, PALB2, and NBN) were those previously shown to be strongly associated with prostate cancer risk in this African ancestry sample." (PMID 38014910, 2023). "In prostate cancer, the frequencies of germline and somatic variants of BRCA1/BRCA2 are almost the same; therefore, evaluation of both germline and somatic variants is necessary." (PMID 37174127, 2023).